BCL2 (BCL2 apoptosis regulator)
Diseases named in the same sentence as BCL2 in open-access papers (continued):
Sharing a sentence is not in itself a finding about the gene and the disease.
gastric cancer (continued). "Western blot analysis further denoted that co-culturing MR macrophages or addition of rhCXCL5 increased the expression levels of anti-apoptotic protein Bcl-2, whereas pro-apoptotic protein Bax was significantly decreased in gastric cancer cells." (PMID 36151545, 2022). "Western blot analysis was performed to detect the expression of claudin 1, c-Myc, cyclin D1, Bcl-2, and caspase-3 proteins in gastric cancer cell lines after treatment with miR-155-5p and Res." (PMID 35789645, 2022). "HSP-treated gastric cancer inhibited cell proliferation by inducing apoptosis by increasing Bax/Bcl-2 ratio, cyt-c,caspase-3, caspase-9, AIF, and Apaf-1 via a mitochondrial-dependent pathway in vitro and xenograft tumours at a dose-dependent manner." (PMID 35128104, 2022). "For a preliminary study of anti-gastric cancer activity of Ova, we focused on the investigation of expression behaviors of the apoptosis-related genes Bcl-2, Bax and caspase-3 induced by the treatment with Ova." (PMID 35163851, 2022). "This can lead to a decrease anti-apoptotic proteins, such as Bcl-2, which consequently seemed to result in apoptosis of gastric cancer cells." (PMID 36135210, 2022). "The Ganoderma lucidum polysaccharide fraction induced the apoptosis of gastric cancer SGC-7901 cells via down-regulating Bcl-2 protein expression and increasing Bax expression." (PMID 36144560, 2022). "Studies have shown that circCCDC66 significantly inhibits B-cell lymphoma-2 (BCL2) mRNA and protein levels by targeting miR-618 to induce cisplatin chemotherapy resistance in gastric cancer cells." (PMID 36698408, 2022). "When AGS human gastric cancer cells were treated with quercetin, anti-apoptotic Bcl-2, Mcl-1, and Bcl-x protein expression were decreased, and pro-apoptotic proteins such as Bad, Bid, and Bax protein expression was increased." (PMID 35971151, 2022). "Carnosine (200 mM) can also induce apoptosis in SGC-7901 and MKN45 human gastric carcinoma cells by reducing Bcl-2 and increasing Bax and PARP protein expression." (PMID 34976156, 2022). "BCL-2 was a target of miR-1271 and miR-503 and mediated the suppressing role of miR-1271/miR-503 in cisplatin resistance of human gastric cancer cells." (PMID 33623790, 2021). "Subsequently, β-catenin signals further up-regulated the expression anti-apoptosis protein BCL2, leading to the chemo-resistance in gastric cancer cells." (PMID 34319913, 2021). "Next, BCL-2 inhibitor YC137 was introduced to examine the role of BCL-2 in trastuzumab resistance of gastric cancer cells." (PMID 33623790, 2021). "An in vitro study showed that altered signal transduction, activation of the Bcl-2/Bax apoptosis-related genes, and induction of cell apoptosis in gastric cancer cells after 125I seed irradiation." (PMID 33968713, 2021). "Consistently, tumor tissues from CR gastric cancer patients revealed higher expression of BCL2 and β-catenin." (PMID 34319913, 2021). "HDACi and knocking down of E2F5 as tumor suppressors inhibited cell proliferation, migration invasion, and blocked the cell cycle in gastric cancer cells by suppressing BCL2." (PMID 34947956, 2021). "There has also been a report on the correlation between increased BCL-2 level and the resistance of chemotherapeutic drugs such as 5-fluorouracil, adriamycin, mitomycin C in gastric cancer." (PMID 34717604, 2021). "Liquiritin (LIQ) has been shown to inhibit drug-induced apoptosis by increasing Bax and reducing Bcl-2 in cisplatin (DDP)-resistant gastric cancer cells." (PMID 34306145, 2021). "It has been found in tissues of gastric cancer that the upregulated expression of BCL2 predicted a poor prognosis." (PMID 34899944, 2021). "This carotenoid exhibited cytotoxic effects and induced G2/M cell cycle and apoptosis in gastric cancer cells by up-regulating several proapoptotic factors, such as Bax, and down-regulating some antiapoptotic proteins, such as Bcl-2, among others." (PMID 34677429, 2021).
gastric cancer (continued). "In contrast, the sequestration of miR-181-a enabled MEG3 to up-regulate Bcl-2 in the case of gastric cancer." (PMID 33422052, 2021). "When gastric cancer occurred, BCL2 inhibited the abnormal apoptosis of gastric mucosal cells by targeting pro-apoptotic proteins to the mitochondrial membrane, thereby preventing the development of gastric cancer." (PMID 34773055, 2021). "oesophageal cancers (via Bcl-2 downregulation and Bax and caspase-3 upregulation), glioblastomas (determined via cell viability assay) and gastric cancers (via COX-2 downregulation)." (PMID 33985540, 2021). "Alteration in the expression of E2F5 results in the activation of the expression of BCL2 in gastric cancer cell lines." (PMID 34947956, 2021). "We sum up different ncRNAs and related moleculars and signaling pathway in gastric cancer, like Bcl-2, PTEN, Wnt signaling." (PMID 34966746, 2021). "PI3K-Akt-mTOR signaling pathway is frequently activated in gastric cancer patients, and can promote the release of free Bcl-2 from Bcl-2/Bcl-xl dimer, and promote the proliferation and growth of tumor." (PMID 33627124, 2021). "Aside from the mentioned target genes, it was already shown that miR-148a promotes apoptosis in colorectal cancer by silencing Bcl-2 and promotes proliferation of gastric cancer cells by targeting p27." (PMID 34135940, 2021). "GSE1 was examined to positively regulate the expression of BCL-2 in HER2-positive gastric cancer cells." (PMID 33623790, 2021). "Constitutive activation of STAT3 and overexpression of its target gene Bcl‐2 and c‐Myc are detected in cisplatin‐resistant gastric cancer cells." (PMID 34375503, 2021). "It has been found that phloretin, a plant-derived natural bioactive product, is an important molecule for the treatment of AGS gastric cancer via expression of Bax and was increased in dose-dependently while the expression of Bcl-2 decreased." (PMID 34572730, 2021). "Functional inhibition of BCL-2 by YC137 dramatically decreased the resistance of trastuzumab-resistant gastric cancer cells to trastuzumab." (PMID 33623790, 2021). "Upregulation of BAX and down-regulation of Bcl-2 by Res are involved in these anti-tumor impacts in implanted human primary gastric carcinoma cells in nude mice." (PMID 33478512, 2021). "Another study demonstrated that miR-429 induced apoptosis of gastric carcinoma cells by targeting Bcl-2." (PMID 33714199, 2021). "Anti-apoptotic protein Bcl-2 plays a substantial role in the carcinogenesis, whereas the regulation for Bcl-2 in gastric carcinoma (GC) is poorly understood." (PMID 33402109, 2021). "The BCL2 and BCLxL expression tended to be less downregulated in gastric cancers with lymph node involvement and BCL2 in more advanced primary tumors." (PMID 32630408, 2020). "Overexpression of PLOD2 upregulated the expression of BCRP protein and inhibited apoptosis by decreasing BAX and increasing the level of Bcl2, enhancing the resistance of gastric cancer cells to 5-FU." (PMID 32284742, 2020). "Knockdown of PLOD2 downregulated the expression of BCRP protein, while increasing BAX and decreasing the level of BCL2 promoted apoptosis, reducing the resistance of gastric cancer to 5-FU." (PMID 32284742, 2020). "Restoration of miR-34 in gastric cancer cells suppresses growth and increased apoptosis through down-regulating expression of Bcl-2, Notch, and high-mobility group AT-hook 2 (HMGA2)." (PMID 32192494, 2020). "For oxaliplatin resistance, the oncogenic miR-27a has been found to enhance MDR properties by inducing MDR1/P-gp, lung resistance protein (LRP) and Bcl-2 expression in gastric cancer." (PMID 32192494, 2020). "Down-regulation of miR-204 was found to correlate with increased expression of Bcl-2 protein in gastric cancers (GCs)." (PMID 32182776, 2020).
gastric cancer (continued). "The IC50 of HA14–1 in BCL2-drug-resistant gastric cancer cell lines was higher than that in normal gastric cancer cell lines." (PMID 33126914, 2020). "The qRT-PCR assay showed that the transcriptional level of MCL1 in BCL2-drug-resistant gastric cancer cell lines was higher than that in normal gastric cancer cell lines." (PMID 33126914, 2020). "Naringenin and epigallocatechin-3-gallate decreased the BCL-2 expression accordingly in gastric cancer (SGC-7901) cells and in cholangiocarcinoma (HuCC-T1) cells." (PMID 32059369, 2020). "For instance, LncRNA MEG3 functions as a ceRNA to suppress gastric cancer progression through sequestering oncogenic miR-181s and up-regulating Bcl-2." (PMID 31868202, 2020). "In gastric cancer cells, ART-mediated apoptosis was associated with down-regulation of CDC25A and Bcl-2 and up-regulation of Bax accompanied by reduced mitochondrial membrane potential levels." (PMID 33316936, 2020). "On the contrary, the IC50 values of BGC‐823 with low Bax expression and other gastric cancer cells with low Bcl‐2 expression were all greater than 10 mmol/L." (PMID 32346976, 2020). "In gastric cancer cells, malvidin promotes an increase in Bax/Bcl-2 ratio, caspase-3 activation, and p38 kinase expression while reducing the ΔΨm and inducing cell cycle blockage at the G0/G1 stage." (PMID 32911639, 2020). "Flavanone hesperetin induced cytochrome c release, activation of caspases-3 and -9, and reduced Bax to Bcl-2 ratio in gastric cancer cells, in the Eca109 cell line as well as in the HT-29, MCF-7, and MDA-MB-231 cell lines." (PMID 32059369, 2020). "We confirmed that PVT1 can regulate the expression of Bcl2 and enhance drug-resistance of gastric cancer to 5-Fu." (PMID 31205469, 2019). "Hu and coworkers 16 demonstrated that silencing of KRT17 in gastric cancer cells inhibited cell proliferation both in vitro and in vivo conditions, reduced the migration of tumor cells and induced apoptosis by BCL2 expression." (PMID 31602265, 2019). "Oridonin significantly inhibited the cell growth and induced apoptosis against human gastric cancer SGC-790 cells via alteration of the Bcl-2/Bax ratio by downregulation of the antiapoptotic Bcl-2 protein and upregulation of the proapoptotic Bax protein." (PMID 31354479, 2019). "Based on the literatures, the present study tried to explore the correlation and impact of miR-1915-3p on Bcl-2, particularly in gastric cancer." (PMID 31036603, 2019). "Our results showed that PVT1 can inhibit the apoptosis and enhance the 5-Fu resistance of gastric cancer through the activation of Bcl2." (PMID 31205469, 2019). "Upregulation of miR-204 increases the chemosensitivity of gastric cancer cells to 5-FU and oxaliplatin through targeted inhibition of Bcl-2." (PMID 31384174, 2019). "The results of western blot analyses showed that the expression of cyclin D1 and Bcl2 was downregulated while that of the active forms of caspase-3 ad PARP was upregulated in DANCR knockdown gastric cancer cells." (PMID 29416741, 2018). "We also confirmed the ability of miR-204 to target Bcl-2, as previously reported in gastric cancer, thus corroborating the correlation between Bcl-2 and Sema5A expression, initially observed in Bcl-2 overexpressing clones." (PMID 30454024, 2018). "The results of quantitative RT-PCR analyses showed that the expression of proliferation-related genes including cyclin D1 and Bcl2 was downregulated while that of apoptosis-related gene Bax was upregulated in DANCR knockdown gastric cancer cells." (PMID 29416741, 2018).
gastric cancer (continued). "Overexpression of miR-204 also led to a decrease in Bcl-2 protein levels, in accordance with published data in gastric cancer." (PMID 30454024, 2018). "Previous studies revealed that melatonin enhanced antitumour effects in human gastric carcinoma cells and murine foregastric carcinoma cells by increasing Bax expression and decreasing Bcl-2 expression." (PMID 30544713, 2018). "ZHX1 has been reported to induce apoptosis and cell cycle arrest (G1/S) by regulating cyclin D1, cyclin E, Bcl2, Bax, and cleaved caspase-3 in gastric cancer, and ZHX2 overexpression was correlated with low expressions of cyclin A and cyclin E in HCC." (PMID 28152006, 2017). "Taken together, evidence suggests that Bcl-2 probably acts as a tumor suppressor gene in gastric cancer." (PMID 28662697, 2017). "The treatment with NS-398 is effective in inhibiting the expression of Bcl-2 while promoting the expression of Bax in human gastric cancer cells." (PMID 29190954, 2017). "Previous studies found that miRNA clusters (miR-15b, miR-16, miR-34, miR-181b, miR-181c, and miR-497) exhibit relatively low expression in gastric cancer and promote the expression BCL-2 which inhibits apoptosis." (PMID 29113415, 2017). "miR-BART20-5p was found to target apoptosis-inducing factor, Bcl2-associated agonist of cell death (BAD) and induce the proliferation of gastric cancer cells by repressing the expression of BAD." (PMID 28757548, 2017). "Collectively these results suggested that the p-STAT3 and Bcl-2 was involved in the execution of apoptotic cell death in CA10 treated SGC-7901 gastric cancer cells." (PMID 29254150, 2017). "Mechanisms of TGF-β induced apoptosis include an increase in the expression of death associated protein kinase DAPK and the binding of the proapoptotic effector to Bcl-2 in gastric carcinoma cell lines." (PMID 28969048, 2017). "For example, miR-204 targets Bcl-2 expression and enhances responsiveness of 5-fluorouracil and oxaliplatin in gastric cancer." (PMID 27083050, 2016). "This point is supported by the previous clue regarding Gas1-induced cell apoptosis due to the Bax/Bcl-2 ratio and caspase-3 activation in gastric cancer." (PMID 27391369, 2016). "BCL2 has also been reported as a direct target of miR-15b using a model of drug resistant gastric cancer cells." (PMID 27195958, 2016). "Western blots showed that B19 dose-dependently decreased the expression of anti-apoptotic proteins Bcl-2 and increased the expression of pro-apoptotic proteins Bax in three gastric cancer cell lines (SGC-7901, BGC-823 and KATO III)." (PMID 26919094, 2016). "In both human adenocarcinoma gastric cancer cells and rat model of gastric cancer, crocetin induced apoptosis, suppressed Bcl-2 and up-regulated Bax expression in gastric adenocarcinoma cells." (PMID 27529277, 2016). "The down-regulation of miR-204 correlated with increased Bcl-2 protein staining in human gastric cancer (GC) specimens." (PMID 25893379, 2015). "This suggests that the overexpression of CDX2 induced apoptosis by altering the Bax/Bcl-2 ratio to suppress gastric cancer growth." (PMID 25738600, 2015). "AKT1 knockdown in gastric cancer cells also increases the expression of Bax and reduces the expression of Bcl2, thus increasing cell death in vitro and in vivo." (PMID 26158514, 2015). "The pro-apoptosis effects of luteolin in gastric cancer cells are related to down-regulation of Bcl-2 expression by decreasing miR-34a expression." (PMID 26305257, 2015). "Studies have also reported that native bLf significantly decreased the levels of intrinsic anti-apoptotic protein Bcl-2 in stomach cancer cells." (PMID 25998617, 2015). "Further large-scale, prospective studies should be performed to validate the usefulness of bcl-2 in detecting tumor recurrence in patients with gastric cancer." (PMID 24555747, 2014).
gastric cancer (continued). "The Bcl-2 expression correlated with stage pT3 and T4 gastric cancer (P < 0.05), with the intestinal type according to Lauren (P < 0.001), ulcerated type according to Bormann's classification (P < 0.01), and with local lymph node metastases (P < 0.05)." (PMID 24741635, 2014). "It is possible that bcl-2 affects gastric cancer recurrence by regulating the tumor cell biological behaviour." (PMID 24555747, 2014). "MiR-148a has been reported to be a tumor metastasis suppressor in gastric cancer, and ectopic expression of miR-148a was shown to induce apoptosis and silence Bcl-2 in colorectal cancer cells." (PMID 24499489, 2014). "In this study, our experimental results showed that gastric cancer MDR cell lines mediated CAM-DR through upregulation of Bcl-2 by MGr1-Ag interaction with laminin." (PMID 24703465, 2014). "Positive Bcl-2 expression was significantly more frequent in patients with more advanced gastric cancer (T3, T4) than in those with less advanced tumors (T1, T2), (37/58; 63.8% versus 12/30; 40%, P < 0.05)." (PMID 24741635, 2014). "It is reported that through targeting bcl-2, miR-181d inhibited neuroglia cell proliferation and promoted apoptosis while miR-15b and miR-16 played a role in the drug resistance of gastric cancer." (PMID 24774218, 2014). "Fourteen of them have been reported for their roles in gastric cancer by the low-throughput experiment, such as miR-204 targets Bcl-2 and SIRT1 with downregulation in gastric cancer." (PMID 24982912, 2014). "The Bcl-2 protein was more frequently expressed in cancer cells in patients with the intestinal type of gastric cancer than in the diffuse type, the difference being statistically significant (42/59; 71.2% versus 7/21; 25.0%, P < 0.001)." (PMID 24741635, 2014). "The depth of invasion, lymph node metastases and expression of bcl-2 are independent factors for predicting gastric cancer recurrence." (PMID 24555747, 2014). "Other known targets of miR-148a include bcl-2, rho-associated protein kinase 1, c-Myc, and HPIP in cancers including gastric cancer, colorectal cancer, and HCC." (PMID 24798342, 2014). "Others found differences even between adenocarcinomas and various histological types of early gastric cancer, showing more frequent expression of Bcl-2 in adenomas and convex form of early cancer, as compared to the recessed form." (PMID 24741635, 2014). "Our results confirm those of previous studies in which isomorellin, forbesione and gambogic acid induced apoptosis through the regulation of Bax (up) and Bcl-2 (down) protein expression in the human gastric carcinoma cell line MGC-803 and in CCA cell lines." (PMID 25866479, 2014). "miRNA-19a/b affects multidrug resistance in gastric carcinoma cells by targeting PTEN through regulation of Bcl-2 and Bax." (PMID 25003395, 2014). "High expression levels of the BCL2 gene, though correlated with less aggression of stomach cancer, had a lot to do with drug resistance of the cancer cells." (PMID 23311997, 2013). "Our previous study has demonstrated that Bcl-2 protein is a direct target gene of miRNA-16 in the development of MDR in SGC7901 gastric cancer cells." (PMID 23613938, 2013). "The enforced expression of miR-449a suppresses gastric cancer cell proliferation and induces apoptosis through directly targeting Bcl-2." (PMID 24260067, 2013). "Particularly in gastric cancer, frequent expression of the BCL2 gene always occurred in malignant tissues." (PMID 23311997, 2013). "A previous study reported that abnormal Bcl-2 expression is an important factor in the biological behavior of gastric carcinoma and that it is capable of regulating apoptosis." (PMID 24260067, 2013). "In our experiment, increasing levels of Caspase-9 and down-regulation of Bcl-2 and Bcl-xL were detected in human gastric cancer cells, indicating that knockdown of AP-4 activated both intrinsic and extrinsic pathways to apoptosis in cancer cells." (PMID 22615908, 2012).